PIK3CA (phosphatidylinositol-4,5-bisphosphate 3-kinase catalytic subunit alpha)
Diseases named in the same sentence as PIK3CA in open-access papers (continued):
Sharing a sentence is not in itself a finding about the gene and the disease.
cancer (continued). "Mutations and/or amplifications of the PI3K catalytic subunits p110α (PIK3CA) and p110β (PIK3CB), the PI3K regulatory subunits p85α (PIK3R1) and p85β (PIK3R2), the PI3K effector AKT (AKT1) are often observed in cancer." (PMID 23658859, 2013). "Indeed, activating KRAS, BRAF and PIK3CA mutations are able to bypass EGFR pharmacological inhibition, thereby resulting in a constitutive activation of the mitogen-activated protein kinase and AKT pathways, known to play a central role in cancer onset and progression." (PMID 22911782, 2012). "At day 10, the strongest suppression of SK-BR-3 growth on the Test Cancer BioChip was observed using siRNAs for ACTB, PIK3CA, and ERBB2." (PMID 23049944, 2012). "SAIC also identified many other cancer driver genes within individual chromosomes (ST 3), such as SKIL, CDK4, PIK3CA, PTEN, FGD4, FGFR1." (PMID 22839576, 2012). "High performance of our resequencing approach is also illustrated by the fact that we identified mutations in known candidate drivers in T-ALL that were included in the collection of known cancer genes such as NOTCH1, FBXW7, PTEN, PHF6, WT1 and PIK3CA." (PMID 22675565, 2012). "PIK3CA and, recently, MTOR have been successfully targeted with selective agents to treat human cancers." (PMID 22912864, 2012). "We recently identified somatic activating mutations in genes associated with the AKT and MAPK signaling pathways, including PIK3CA, KRAS, HRAS, and NRAS, in BM from breast and other cancers." (PMID 22567347, 2011). "In conclusion, our results on overexpression of PIK3CA in PTC, suggest that this gene is involved, to some degree, in pathogenesis of PTC, likewise in more aggressive types of the cancer in question." (PMID 20804548, 2010). "Again, annotation to OMIM revealed that several cancer-related genes were involved in these LOH regions (MLH1, ZMAT3, ADCY7, PIK3CA)." (PMID 20428235, 2010). "We will first discuss the evidence describing altered PI3K signaling in human cancer, before more specifically addressing alterations in PTEN, PIK3CA and the p85 regulatory subunit of PI3K." (PMID 19384426, 2007). "With regard to the clinical stage, the prevalence was significantly higher in stage IV carcinomas as compared to stage I–III carcinomas (CCNL1: P<0.001; SNO: P=0.05; PIK3CA: P=0.009; TP73L: P=0.03)." (PMID 15700036, 2005). "In contrast, carcinoma cell lines did not undergo apoptosis upon PI3K inhibition, except for PIK3CA-mutated cell lines." (PMID 41916029, 2026). "Notably, PIK3CA and HER2 were downregulated by FEO-CSNPs, suggesting an inhibitory effect on pathways critical for cancer cell growth." (PMID 40284420, 2025). "The relative expression levels of PIK3CA, AKT, PTEN, VEGFA, NOTCH1, and HES1, as the key cellular signaling pathways involved in cancer biology, angiogenesis, and cell survival/proliferation, were investigated to determine the effects of SCC, DOK, and HaCaT products on fibroblasts." (PMID 40729037, 2025). "Among the collection of genes, the aberrant nature of PIK3CA and MAPK1 in luminal and HER2 BCs is the key player in the oncogenicity of BC development, underscoring the potential of OT as a therapeutic agent for targeted cancer treatment." (PMID 40427676, 2025). "Seven other cancer-related genes (BRAF, NRAS, HRAS, ERK1, ERK2, PTEN, and PIK3CA) were found negative for mutations." (PMID 40364006, 2025).
cancer (continued). "Genetic alterations in key components of these pathways, such as EGFR, BRAF, KRAS, PIK3CA, and PTEN, have been well-documented in NSCLC, and our study suggests that CKS1B may play a role in modulating these alterations to drive cancer progression." (PMID 40165937, 2025). "Regular use of ASA increased CRC-specific and overall survival in these patients, while wild-type PIK3CA cancer patients did not benefit." (PMID 38791445, 2024). "Additionally, after assessing the mRNA levels of selected genes, we compared the PIK3CA, PTEN, and FOXO1 protein expression between cancer and normal tissue using images from the Human Protein Atlas." (PMID 38891994, 2024). "A significant increase in the frequency of somatic copy number alterations was observed in the known cancer drivers NOTCH1, PPP6C, RAC1, EIF4G1, and PIK3CA in the transition from potentially premalignant (oral) lesions to HNSCC, which was correlated with their expression." (PMID 39613893, 2024). "Interestingly, the distributions of several known cancer driver genes exhibit significant differences between cancer and normal tissues, such as FAT4, KMT2C, KMT2D, KRAS, PIK3CA, and PTEN." (PMID 39541191, 2024). "We selected PIK3CA as our gene target due to its widespread prevalence as an oncokinase across various cancer types and its lack of presence as a gene target in clinical trials." (PMID 38671743, 2024). "PIK3CB has gained more attention in recent years for which more studies proved that PTEN-deficient cancers depend on PIK3CB, not PIK3CA 17,18." (PMID 38356702, 2024). "Somatic genetic variations in APC, KRAS, BRAF, and PIK3CA genes are the most frequent in CRC, leading to the activation of key WNT–β-catenin and MAPK signal transduction pathways, which subsequently promote cell proliferation and cancer progression." (PMID 37863651, 2024). "Compared with the wild-type control, mutated PIK3CA promoted the growth, migration and invasion of SCC cells, irrespective of the mutation site or cancer type." (PMID 38616230, 2024). "This meta-analysis aimed to assess the impact of the most relevant molecular alterations in cancer-related genes of CRC (i.e., RAS, BRAF, SMAD4, PIK3CA) as prognostic markers of survival and disease recurrence in patients with mCRC surgically treated by LM resection." (PMID 39220128, 2024). "RAC2 also showed upregulation of proliferative pathways, including signalling by NTRK2/TRKB, characterised by overexpression of the PIK3CA gene, and signalling by ERBB2 in cancer, as reflected by elevated serum concentrations of SHC1, ERBB4, EGFR and ERBB2, compared with RAC3." (PMID 39401856, 2024). "In agreement with our results, all the studies showed that ZEB1‐circRNAs are upregulated in cancer; however, they identified different targets and functional axes (miR‐337‐3p/TGFBR1, mR‐195‐5p/LOXL2, miR‐448/EEF2K, miR‐200a‐3p/CDK6 and miR‐199a‐3p/PIK3CA)." (PMID 37408496, 2023). "Pan-cancer analyses have shown that MYC is the 3rd most frequently amplified gene in malignant neoplasms, and its alterations are mutually exclusive with other genetic drivers like PIK3CA, PTEN, APC or BRAF." (PMID 37443779, 2023). "For GP5, CDK12 inactivation and gains of AKT1, GSK3B, PIK3CA, CCND1, and MDM2 were identified as the top truncal druggable targets that would be most likely to obtain a durable response due to their presence in all cancer cells." (PMID 37828555, 2023).
cancer (continued). "While p110α activity is critical to sustaining tumor growth in PIK3CA-mutant cancer cells, tumors lacking PTEN function become dependent on p110β for PI3K signaling and cell proliferation." (PMID 36913051, 2023). "This gene set contained well-known cancer driver genes ARID1A, PTEN, PIK3CA, and CTNNB1." (PMID 37444632, 2023). "Nevertheless, recent findings have shown that endometriotic lesions without concurrent cancers contain cancer-associated somatic mutations including for KRAS, PTEN, ARID1, and PIK3CA." (PMID 36788175, 2023). "It has also been displayed to be efficient against HER2 negative and positive cancers and PIK3CA mutant." (PMID 37228871, 2023). "To further explore the mechanism of compound XIN-10 in inhibiting cancer cell proliferation, we treated MCF-7 cells with XIN-10 at concentrations of 0.3 and 0.6 μM for 24 h and analyzed the expression patterns of the PIK3CA and mTOR1 genes using fluorescence quantitative PCR." (PMID 37834269, 2023). "As a result of SCNV of NRGs in pan-cancer, we found SCNV gain in DNASE1, HMGB1 and PIK3CA." (PMID 37408763, 2023). "These patients, however, did not have inferior survival compared to patients with PIK3CA wild-type cancers." (PMID 37178424, 2023). "PIK3CA, CBFB, CDC27, MAP3K1, and ESRRA were among the genes that were cancer drivers." (PMID 37454130, 2023). "therefore, realizing downregulation of PIK3CA and ABCB1 by knocking out CDK6 in MDR cancer cells overexpressing ABCB1 might benefit combined chemotherapy against cancer cells with ABCB1-mediated MDR." (PMID 35459184, 2022). "Among them, FOS-promoting cell autophagy was upregulated, whereas PI3K (PIK3CA/PIK3CB), which is a key signaling factor in cancer and was found to regulate ABCB1-mediated MDR in our recent study, was downregulated accompanying the remarkable downregulation of ABCB1." (PMID 35459184, 2022). "Genetic alterations of the PIK3CA, mTOR, PTEN, AKT1, AKT2, and AKT3 genes in human cancers." (PMID 35402264, 2022). "For the three cancers, SNVs were more likely to be detected in the high-OGT expression group than in the low-OTG expression group, and the top five genes with the highest frequency of SNV were MUC17, PIK3CA, SI, SYNE1, and PTEN." (PMID 35356257, 2022). "Molecular aberrations that were shared in at least one P/X pair and that were previously recognized to have deleterious effects in human cancers included CHEK2 [K416E; 415S (SNP)], EGFR (158N), ATM (P1054R), STK11 (D194N), PIK3CA (E545K), KIT (798I; M541L), and RUNX1 (L56S)." (PMID 34714554, 2022). "Furthermore, our identification of higher rates of PIK3CA mutations may suggest that understanding the specific pathways that are altered with immunosuppressive agents may lead to new pathway specific immunosuppression that will reduce the increased risk for CRC and other cancers." (PMID 36661655, 2022). "The following most altered cancer genes were LRP1B (26%), PIK3CA (24%), CDKN2A (24%), PTPRD (15%), RB1 (13%), PDE4DIP (13%), PCLO (11%), KRAS (11%), FAT1 (10%), and RELN (10%), and these results partially overlap with the most altered genes depicted in the experimental cohort." (PMID 35330454, 2022).
cancer (continued). "Third, data on the predictive role of PIK3CA-mut/gain to alpelisib from BC and pan-cancer cells and PDX are not univocal and data from patients treated with alpelisib derive from very limited and non-randomized cohorts." (PMID 35181669, 2022). "In early-stage cancers, NNMT expression is higher in BRAF-mutated than in BRAF wild type tumors but is not affected by KRAS or PIK3CA mutation status." (PMID 35177765, 2022). "BRAF mutant cancers have been divided in two subsets, based on unsupervised genomic clustering, that do not correlate with their MSI status or PIK3CA mutation status." (PMID 36079062, 2022). "MiR-183 is related to cancer progression by repressing the expression of PTEN and PIK3CA." (PMID 36556276, 2022). "Herein, our study reveals the impact of COL11A1 gene product in the alteration of PTEN, PIK3CA, KRAS, and BRAF which might downregulate the RTK-RAS-PI3K signaling pathways to induce cancer development." (PMID 33597969, 2021). "Collectively, these findings suggest that PIK3CA and SLC6A6 may promote the development of chemoresistance, in part through the regulation of EMT and cancer stemness." (PMID 34571860, 2021). "Interestingly, all significant results targeted known cancer driver genes such as EGFR, HER2, PIK3CA, and BRAF." (PMID 33872312, 2021). "Ultimately, we show that HER3 inhibition and PD-1 blockade may provide a multimodal precision immunotherapeutic approach for PIK3CA wild type HNSCC, aimed at achieving durable cancer remission." (PMID 33888713, 2021). "Among the 72 samples, 32 contained driver mutations in well-known cancer genes in NSCLC, such as EGFR (n = 26; E709G, T790M, L858R and non-frameshift deletions of exon 19), and PIK3CA (n = 4; E542K and G1049R)." (PMID 33407425, 2021). "However, the great majority of PIK3CA mutations are concentrated in a few hotspot codons and almost the totality of the remaining mutations is classified as probably oncogenic, strongly suggesting that they are not passenger mutations occurring by chance in hypermutated cancers." (PMID 33435133, 2021). "Surprisingly, increased TMB in PIK3CA mutated cancers does not translate to clearly better survival outcomes, implying that any positive influence of the hypermutated phenotype may be neutralized by other factors in the PIK3CA mutated cellular micro-environment." (PMID 33435133, 2021). "For instance, a combination of glutaminase (GLS) inhibitor CB839 and 5-FU chemotherapy drug increases the anti-cancer effect on the xenograft growth of PIK3CA-mutant CRC cells without significant dose-limiting toxicity." (PMID 34887764, 2021). "PTEN loss was, in fact, a better predictor of resistance to A66, which is consistent with previous studies in other tumour types where knockdown on PIK3CA did not affect PI3K signalling in several PTEN null cancer lines." (PMID 33549048, 2021). "Besides the genes encoding ZAPs, we also detected five genes encoding signaling molecules involved in the immune response to cancer, namely TRAF6, EIF2AK2, PIK3CA, APAF1, and POU2F2." (PMID 34844636, 2021).
cancer (continued). "Importantly, these are predictive biomarkers for drugs that are currently in use for treating different cancers, such as PARP, ERBB2, EGFR, PIK3CA, mTOR, and Hedgehog signaling inhibitors." (PMID 34575676, 2021). "Mutation in PIK3CA and independent activation of the PI3K pathway only (without Akt) can also induce cancer." (PMID 34830339, 2021). "These genes include very well-known cancer related oncogenes such as BRAF, ERBB2, AKT1 and PIK3CA with the genes which are not listed in the cancer gene census list of the COSMIC database." (PMID 32998690, 2020). "Taken together, miR-584 may have an unvalidated cancer-related targetome that includes PTEN, CCND1, PIK3CA and STAT1." (PMID 32615958, 2020). "The genomic identification of significant targets in cancer analyses (GISTIC) led to identify recurrent focal deletions (3p14.2 (FHIT), 11q11, and 4q13.2) and focal amplifications (17q13 (ERBB2), 8q24.21 (MYC), 3q26.31 (PIK3CA, TRAIL), 8q24.22, 8q21.13)." (PMID 32647357, 2020). "An important difference between cancer and developmental disorders such as PROS, CLVM, VM and LM is that these congenital lesions are characterized by a single copy of the mutant PIK3CA (heterozygous), while human cancer often contains multiple oncogenic hits along the same pathway." (PMID 32350708, 2020). "It was previously reported that glutamine deprivation significantly reduces the proliferation of PIK3CA mutant, but not the wild type, cancer cells." (PMID 32365457, 2020). "PIK3CA and PIK3R1 are centrally involved in several cancers." (PMID 32962181, 2020). "Additionally, PIK3CA and PTEN are known regulators of PI3/AKT signaling, which is a key regulatory pathway that can promote cancer growth and proliferation." (PMID 32626534, 2020). "Additional mutations were identified in PIK3CA (six patients) and in HIST1H2BB, HIST1H2BC, and SMARCB1 (one patient each), but none were found in other frequently mutated genes in cancer." (PMID 32235312, 2020). "Comparing with cancer cells without driver gene mutation, those with a mutation, such as EGFR, ERBB2, TGFbR2, MET, RAS, RAF, PIK3CA, and PTEN genes, can proliferate under limiting nutrient concentrations." (PMID 33537237, 2020). "Transcriptome analysis of CKI-treated MDA-MB-231 cells revealed that PIK3CA, AKT1, and MAPK1 all affect cell migration, which may be related to the role of CKI in the treatment of cancer." (PMID 32020871, 2020). "Furthermore, mutations were detected in genes that are known for their involvement in other cancer types, such as TERT, KMT2D, PIK3CA, AKT1, CTNNB1 and NR1D1." (PMID 32455687, 2020). "MEK inhibitor treatment induced cell death in PIK3CA wt cancer cells, whereas PIK3CA mt cells did not respond to MEK inhibitor treatment." (PMID 30944457, 2019). "Furthermore, the results show DawnRank missed more than one significant cancer driver genes including PTEN, PIK3CA and AKT1." (PMID 31888619, 2019). "Although monotherapy with PIK3CA inhibitors has led to poor response, implementation of strategies where PI3K inhibition is tailored as per the cancer type and patients might lead to better response." (PMID 31905960, 2019). "In fact, parental SW48 and LIM1215 cancer cells were significantly sensitive to cetuximab, panitumumab, SYM004 and MM-151 antibodies inducing growth inhibition, as expected being “quadruple wild type” for KRAS, BRAF, NRAS and PIK3CA genes." (PMID 31164152, 2019).